ZNG1B (Zn regulated GTPase metalloprotein activator 1B)
Description:
Zinc chaperone that directly transfers zinc cofactor to target metalloproteins, thereby activating them. Catalyzes zinc insertion into the active site of methionine aminopeptidase METAP1, which function to cleave the initiator methionine from polypeptides during or after protein translation. Mechanistically, the N-terminal psi-PxLVp motif binds to the C6H2-type zinc finger of inactive form of METAP1. After formation of the docked complex, zinc is transferred from the CXCC motif in the GTPase domain of ZNG1B to the zinc binding site in the peptidase domain of METAP1 in a process requiring GTP hydrolysis. GTP/GDP exchange is required for release of active METAP1.
Synonyms: CBWD2
Tractability: Antibody: the Human Protein Atlas places it where antibodies can reach. PROTAC: ubiquitination databases record sites on it.
Gene: Protein-coding gene on chromosome 2 (113,437,691 to 113,496,204, forward strand). Ensembl gene ENSG00000136682.
Subcellular location: Nucleus
Subcellular location (Human Protein Atlas): Plasma membrane
Gene Ontology:
Molecular function: GTPase activity; zinc chaperone activity; zinc ion binding
Biological process: protein maturation
Cellular component: nucleus
Genetic constraint (gnomAD): Loss-of-function variants: 10 observed, 29.66 expected, observed/expected ratio (o/e) 0.34, 90% interval 0.21 to 0.57. The upper end of that interval is the gene's LOEUF score, 0.57, which puts it in group 2 of 6, group 1 being the genes least tolerant of losing a copy. Missense variants: 138 observed, 239.47 expected, observed/expected ratio (o/e) 0.58, 90% interval 0.5 to 0.66. Synonymous variants: 61 observed, 83.63 expected, observed/expected ratio (o/e) 0.73, 90% interval 0.59 to 0.9.
Homologues: Paralogues in human: ZNG1A (98% identical), ZNG1C (98% identical), ZNG1E (98% identical), ZNG1F (97% identical).
Diseases named in the same sentence as ZNG1B in open-access papers:
ZNG1B is named in the same sentence as 2 diseases in open-access papers, as found by Europe PMC text mining. Sharing a sentence is not in itself a finding about the gene and the disease.
ZNG1B shares sentences with these, for which no sentence is quoted: measles (1 paper); type 2 diabetes (1).